SIRT1 (sirtuin 1)
Diseases named in the same sentence as SIRT1 in open-access papers (continued):
Sharing a sentence is not in itself a finding about the gene and the disease.
bronchiectasis (4 papers, 2021 to 2025). Segmental, irreversible dilation of the bronchial tree resulting in the accumulation of secretions which leads to obstruction. "The published study documented a reduction in SIRT1 expression in bronchiectasis, but the association with the clinical characteristics has not been outlined." (PMID 35071262, 2021). "We sought to determine the patterns of SIRT1 and other aging markers in systemic circulation and airways and their expression levels associated with bronchiectasis severity and exacerbation." (PMID 35071262, 2021). "The purpose of this study was to identify the levels of MMP-9, known to cause bronchial damage in chronic pulmonary illness, and SIRT-1, an anti-aging and anti-infective regulatory protein, in patients with bronchiectasis and to evaluate the importance of these biomarkers in diagnosis." (PMID 40290232, 2025). "This is the first study to examine serum MMP-9 and SIRT-1 levels together in individuals suffering from bronchiectasis." (PMID 40290232, 2025). "Since it has been proven that SIRT-1 can affect inflammatory pathways by inhibiting NF-κB activity, it can be concluded that decreased SIRT-1 activity and high MMP-9 levels are associated with increased inflammatory conditions in bronchiectasis patients." (PMID 40290232, 2025). "Serum SIRT-1 and MMP-9 levels were compared between healthy individuals and bronchiectasis patients, and the diagnostic sensitivity of these tests was assessed." (PMID 40290232, 2025). "In comparison to the control group, it was observed that the bronchiectasis group had a lower serum SIRT-1 levels (p<0.001)." (PMID 40290232, 2025). "SIRT-1 levels were considerably lower in bronchiectasis patients compared to the control group (p<0.05)." (PMID 40290232, 2025). "This cross-sectional substudy showed that patients with bronchiectasis yielded a downregulation of SIRT1 in both the systemic circulation and different sites of bronchial epithelium in bronchiectasis, which remained valid after adjustment with the lung age." (PMID 35071262, 2021). "In spite of this, the markedly reduced SIRT1 expression in patients with bronchiectasis as compared with the disease controls suggested that this findings pertaining to the role of SIRT1 in mediating accelerated aging in bronchiectasis remained valid." (PMID 35071262, 2021). "Compared with healthy controls, the relative telomere length (median: 0.88 vs. 0.99, p = 0.009), SIRT1 (median: 0.89 vs. 0.99, p = 0.002), and Ku80 (median: 0.87 vs. 0.96, p < 0.001) expression levels were consistently lower in patients with bronchiectasis." (PMID 35071262, 2021). "Sensitivity analysis that restricted the comparison with the 132 patients with bronchiectasis still demonstrated a significant between-group difference in SIRT1 and Ku80 expression (p < 0.05)." (PMID 35071262, 2021). "Accelerated aging, evidenced by telomere shortening, increased p21, and decreased sirtuin 1 (SIRT1) expression, has also been identified in large airways of patients with bronchiectasis." (PMID 35071262, 2021). "In this study, we profiled SIRT1 and a panel of other aging markers in PBMCs and the bronchiectatic epithelium in adults with bronchiectasis." (PMID 35071262, 2021). "In spite of these limitations, this study demonstrated lower percentage of cells staining positive for SIRT1 in patients with bronchiectasis, suggesting that the reduction in SIRT1 expression would have been more prominent." (PMID 35071262, 2021). "However, we did not need to assess inflammatory marker levels since our goal was to evaluate MMP-9 and SIRT-1 levels, examine their levels among the patient control group, and determine their relevance in the diagnosis of bronchiectasis." (PMID 40290232, 2025). "This study examined bronchiectasis SIRT-1 and MMP-9 levels and its relationship to age and gender." (PMID 40290232, 2025).
bronchiectasis (continued). "Taking into account the levels in the control and patient groups, we concluded that elevated inflammation, which is anticipated to occur in bronchiectasis, may cause MMP-9 levels to increase and SIRT-1 levels to decrease." (PMID 40290232, 2025). "SIRT1 expression in PBMCs is downregulated in patients with bronchiectasis." (PMID 36457607, 2022). "Within the bronchial epithelium, the percentage of positively stained cells was lower for SIRT1 (median: 25.1 vs. 57.2%, p < 0.05) and numerically lower for p16 (median: 40.0 vs. 45.1%) and p21 (median: 28.9 vs. 35.9%) in patients with bronchiectasis than in disease controls (p > 0.05)." (PMID 35071262, 2021). "The percentage of positively stained cells was markedly lower for SIRT1 (median: 25.1 vs. 57.2%, p < 0.05) and nominally lower for p16 (median: 40.0 vs. 45.1%) and p21 (median: 28.9 vs. 35.9%) in patients with bronchiectasis than in disease controls (p > 0.05)." (PMID 35071262, 2021). "Furthermore, the relative telomere length [AUC: 0.62 (95% CI: 0.54–0.71)], SIRT1 [0.64 (95% CI: 0.56–0.72)], and Ku80 [0.68 (95% CI: 0.59–0.76)] modestly discriminates patients with bronchiectasis from healthy controls." (PMID 35071262, 2021). "These indicated the dissociation between SIRT1 expression and bronchiectasis severity." (PMID 35071262, 2021). "This current study in bronchiectasis aimed to evaluate the role of SIRT-1, which may have a critical function in regulating inflammation and other pathophysiological pathways, and the neutrophil-derived protease MMP-9, which is known to cause bronchial damage in various lung diseases." (PMID 40290232, 2025). "MMP-9 and SIRT-1 may be potential biomarkers in the diagnosis of bronchiectasis." (PMID 40290232, 2025). "SIRT1 expression could be measured in adults with bronchiectasis as a marker of accelerated aging." (PMID 35071262, 2021). "This work provides crucial information to illustrate the possible roles of these biomarkers in the pathophysiology of the illness by comparing the serum SIRT-1 and MMP-9 levels in bronchiectasis patients with those in healthy persons." (PMID 40290232, 2025). "In certain areas, more research is required, even if this work is a valuable beginning point for comprehending the possible involvement of SIRT-1 and MMP-9 in the pathophysiology of bronchiectasis." (PMID 40290232, 2025). "This study’s primary merit lies in its contribution to the sparse literature by comparing blood SIRT-1 and MMP-9 levels between bronchiectasis patients and healthy controls." (PMID 40290232, 2025). "Since the AUC value of SIRT-1 levels is less than <0.5 (AUC=0.238), its use as a marker in the diagnosis of bronchiectasis is not statistically significant." (PMID 40290232, 2025). "When analyzed from a clinical standpoint, it might offer a fresh viewpoint on whether SIRT-1 and MMP-9 can be employed as biomarkers in bronchiectasis patients." (PMID 40290232, 2025). "Furthermore, research is required to assess the changes in SIRT-1 and MMP-9 levels in other bronchiectasis phenotypes, such as inflammatory or infectious forms." (PMID 40290232, 2025). "Likewise, sirtuin 1 (SIRT1) expression, which is frequently downregulated in aging, is downregulated in peripheral blood of bronchiectasis patients as well as in their airways." (PMID 36066919, 2022). "The percentage of positively stained cells for SIRT1 correlated positively with that of p16 and p21 (p > 0.05), but not between SIRT1 and p16 in patients with bronchiectasis." (PMID 35071262, 2021). "We have revealed markedly reduced SIRT1 but not p16 or p21 in bronchial epithelium, which partially differed from the findings of reduced SIRT1 expression but higher p21 expression in patients with bronchiectasis." (PMID 35071262, 2021). "SIRT1 failed to discriminate patients with mild-to-moderate from severe bronchiectasis." (PMID 35071262, 2021).
bronchiectasis (continued). "Moreover, the reduced SIRT1 expression was not tempered significantly by the inclusion of disease controls and the markedly greater age in patients with bronchiectasis." (PMID 35071262, 2021). "Stratification of patients into mild-to-moderate and severe bronchiectasis revealed the differential expression in the relative telomere length, Ku70, and TERT (p < 0.05), but not SIRT1." (PMID 35071262, 2021).
deafness (4 papers, 2020 to 2024). An inherited or acquired condition characterized by the complete loss of the ability to hear from one or both ears. "This study identified the roles of miR-204-5p and SIRT1 in deafness in C57BL/6 mice and investigated the loss of cochlear outer hair cells and the involvement of apoptosis and ERS in deafness." (PMID 39531447, 2024). "The protective effect of SIRT1 in cisplatin-induced hearing loss and noise-induced deafness confirms the potential therapeutic role of SIRT1 in the cochlea." (PMID 36204138, 2022). "This study investigated the effect of miR-204-5p-mediated silencing of SIRT1 on the development of deafness in C57BL/6 mice and the roles of miR-204-5p and SIRT1 in deafness." (PMID 39531447, 2024).
diabetic encephalopathy (4 papers, 2020 to 2022). A brain disease that is characterized by functional impairment of cognition, cerebral signal conduction, neurotransmission and synaptic plasticity, and underlying structural pathology associated with diabetes. "In conclusion, current experimental results indicated that SIRT1/ER stress is a promising mechanism involved in quercetin-treated diabetic encephalopathy." (PMID 32312941, 2020).
diabetic foot (4 papers, 2021 to 2026). A diabetic foot is a foot that exhibits any pathology that results directly from diabetes mellitus or any long-term (or "chronic") complication of diabetes mellitus. "Results of a meta‐analysis indicated the SIRT1 rs12778366 is negatively associated with diabetic foot ulcer." (PMID 39474345, 2024). "Activation of the SIRT1/Nrf2 signaling pathway has been demonstrated to promote diabetic foot ulcer healing." (PMID 41598272, 2026). "HDAC2 inhibition can also upregulate SIRT1 expression and ensure SIRT1-mediated protection against diabetic foot ulcers." (PMID 34071497, 2021). "However, the SIRT1/EZH2 axis has hardly been studied in the study of diabetic foot." (PMID 37985432, 2024).
dry eye (4 papers, 2022 to 2025). "Patients with dry eye in this study also had a significant decrease in SIRT1 RNA levels compared to controls." (PMID 38254630, 2023). "Resveratrol alleviates mitochondrial dysfunction by promoting SIRT1 expression, thus reducing ocular surface injury in mice with dry eye." (PMID 35664941, 2022). "Due to the reversal of depressive behaviors and dry eye symptoms in mice, we speculated that luteolin might act on Sirt1 protein to treat depression-related dry eye disorder in mice." (PMID 36641776, 2023). "Here, we also observed decreased expression of SIRT1 in HCEpiCs from a hyperosmolarity culture and DED mouse model, which was accompanied by increased levels of oxidative stress, apoptosis, or dry eye syndrome." (PMID 35664941, 2022).
focal segmental glomerulosclerosis (4 papers, 2023 to 2025). A renal disorder characterized by sclerotic lesions in the glomeruli. "METTL14 orchestrates fibrosis through divergent mechanisms: MAPK/ERK activation via TUG1 regulation in diabetic kidney disease, Sirt1 suppression in focal segmental glomerulosclerosis, and BPTF-driven glycolytic reprogramming in RCC." (PMID 40895041, 2025). "SIRT1 expression is notably decreased in kidney biopsies from patients with focal segmental glomerulosclerosis (FSGS)." (PMID 40218970, 2025). "In focal segmental glomerulosclerosis (FSGS), mechanistically dysregulated m6A dynamics contribute to glomerular dysfunction through METTL14-mediated m6A modifications that suppress Sirt1 expression-a nephroprotective deacetylase-in both murine models and human podocytes." (PMID 40895041, 2025).
gastric adenocarcinoma (4 papers, 2017 to 2024). "SIRT1 in patients with gastric adenocarcinoma was demonstrated to be able to play the role of cancer suppressor through the interaction with β-catenin, which is a significant regulator of the Wnt signaling pathway, which is important in cell adhesion." (PMID 36499440, 2022). "SIRT1 expression was significantly correlated with poor overall survival (OS) in stomach adenocarcinoma patients and poor recurrence-free survival (RFS) in kidney renal papillary cell carcinoma patients (p < 0.05)." (PMID 32151067, 2020). "This hypothesis can explain how the expression of SIRT1 and cytoplasmic β-catenin is correlated in patients with gastric adenocarcinoma and how patients with SIRT1 and β-catenin have better survival rates." (PMID 36499440, 2022).
glomerular disease (4 papers, 2020 to 2023). "On the other hand, attention should be given when using SIRT1 agonists as therapeutic targets for glomerular diseases since they can stimulate renal fibrogenesis." (PMID 38114708, 2023). "Moreover, SIRT1−/− mice podocytes showed increased F-aktin accumulation and albuminuria in comparison with WT mice with glomerular disease, which indicates an increased damage to the cytoskeleton in the absence of SIRT1." (PMID 34685718, 2021).
HCMV infection (4 papers, 2013 to 2025). "Upon EX-527 mediated inhibition of SIRT1 activity in HCMV infection, there was a decrease in the IAV infection, suggesting a protection of SIRT1 across different types of virus." (PMID 30841513, 2019). "Transfection of miR-217 inhibitor not only depressed cellular migration and tube formation induced by HCMV infection, but also enhanced SIRT1 and FOXO3A protein expression." (PMID 24376725, 2013). "In summary, HCMV infection of endothelial cells induces angiogenesis by both of miR-217/SIRT1 and miR-217/FOXO3A axis." (PMID 24376725, 2013). "These experimental results suggest that downregulation of SIRT1 by HCMV infection enhanced ICAM-1 expression, thereby inducing EC motility and tube formation." (PMID 24376725, 2013). "In the present study, we describe a novel mechanism whereby HCMV infection, via miR-217, regulates angiogenic response of endothelial cells by altering SIRT1 and FOXO3A." (PMID 24376725, 2013). "Together, our experimental data suggest that HCMV infection promoted expression of these pro-angiogenic cytokines through downregulation of SIRT1, eventually inducing angiogenesis of ECs." (PMID 24376725, 2013). "We found that HCMV infection of endothelial cells(ECs) enhanced expression of miR-217 and reduced SIRT1 and FOXO3A protein level in 24 hours post infection(hpi)." (PMID 24376725, 2013). "We demonstrated that HCMV infection promotes angiogenesis by reduction of SIRT1 and FOXO3A." (PMID 24376725, 2013). "We next evaluated whether HCMV infection mediates angiogenic response of ECs through SIRT1." (PMID 24376725, 2013). "However, the role of SIRT1 in angiogenesis induced by HCMV infection has not been extensively studied." (PMID 24376725, 2013).
Hodgkins lymphoma (4 papers, 2014 to 2024). A heterogeneous group of malignant lymphoid neoplasms of B-cell origin characterized histologically by the presence of Hodgkin and Reed-Sternberg (HRS) cells in the vast majority of cases. "SIRT1 showed high nuclear expression in patient samples of Hodgkin’s lymphoma; once evaluated together with FOXP3 expression, SIRT1 inhibition can decrease the actions of T-reg cells." (PMID 36230534, 2022). "A recent report showed that SIRT1 inhibition is involved in resveratrol-induced cell death in Hodgkin lymphoma (HL)-derived L-428 cells." (PMID 24603648, 2014).
hypogonadotropic hypogonadism (4 papers, 2018 to 2024). Abnormal ovarian or testicular function due to insufficient hormonal stimulation from the hypothalamic-pituitary axis. "In line with it, Sirt1-deficient mice exhibited central hypogonadism due to aberrant migration of GnRH neurons to the hypothalamus, suggesting that SIRT1 may play an important role in the regulation of the reproductive axis." (PMID 35207605, 2022). "Interestingly, genetic loss-of-function studies in mice had previously suggested a developmental role of SIRT1 in early stages of GnRH neuron maturation; mice with congenital Sirt1 deficiency display hypogonadotropic hypogonadism (HH) due to defective neuronal migration." (PMID 30305620, 2018).
liver failure (4 papers, 2016 to 2025). A liver disease characterized by the liver losing or has lost all of its function. "Albumin-Cre (AlbCre)-induced genetic disruption of Sirt1 in hepatocytes also led to significant protection against GalN/LPS-induced liver failure." (PMID 27711079, 2016). "Seven differentially expressed ferroptosis-related genes (Hmox1, Epas1, Sirt1, Slc3a2, Jun, Plin2 and Zfp36) were obtained through the intersection of ferroptosis-related genes in the FerrDb database with DEGs in the GSE60088 dataset, and all of these genes were up-regulated in liver failure." (PMID 35923893, 2022).
lung squamous cell carcinoma (4 papers, 2015 to 2024). "A study in uranium miners with radon exposure found SIRT1 rs7097008 to be associated with the risk of squamous cell carcinoma of the lung, as one of several variants tested, including rs10997870 and rs1277836645." (PMID 30410074, 2018).
muscular atrophy (4 papers, 2021 to 2025). "Initially, they generated SIRT1 transgenic mice, a mice model with higher SIRT1 muscle level, and then they observed that this modification resulted in a fiber shift from fast-to-slow twitch, which prevents muscular atrophy and dystrophy." (PMID 34205021, 2021). "During catabolic muscular atrophy, DEXA treatments have reported decreased mRNA expressions of SIRT1 and myostatin and muscular mass." (PMID 34066110, 2021). "In diethoxycarbonyl-1,4-dihydrocollidine (DDC) diet-fed KK-Ay mice, a model of skeletal muscle atrophy, semaglutide restored intramuscular mRNA and protein levels of PGC-1α, mitochondrial transcription factor A (mtTFA), and sirtuin 1 (SIRT1), key regulators of mitochondrial biogenesis." (PMID 41011082, 2025).
nephrosclerosis (4 papers, 2020 to 2022). Hardening of the kidney due to infiltration by fibrous connective tissue (fibrosis), usually caused by renovascular diseases or chronic hypertension. "Vasko and colleagues confirmed that restoration of MMP-14 expression in SIRT1-depleted mice improved the angiogenic and matrilytic functions of the endothelium, prevented renal dysfunction, and attenuated nephrosclerosis." (PMID 32802201, 2020). "SIRT1 has been shown to be a key regulator of vascular endothelial homeostasis, improving angiogenesis 22, 35, preventing renal dysfunction, and attenuating nephrosclerosis." (PMID 32802201, 2020).
non-melanoma skin carcinoma (4 papers, 2014 to 2022). "This is important because overexpression of SIRT1 has been reported in a variety of cancers, including non-melanoma skin cancers." (PMID 24743044, 2014). "SIRT1 is also overexpressed in non-melanoma skin cancers, including squamous and basal cell carcinomas, actinic keratosis, and especially in Bowen's disease." (PMID 24743044, 2014).
periodontal disease (4 papers, 2022 to 2025). "An increase in levels of SIRT1 is shown to prevent the progression of periodontal disease in an animal study." (PMID 35630070, 2022). "SIRT1 activation by regular physical exercise could possibly be an important factor in reduced periodontal disease progression, as seen in animal models with physical activity." (PMID 38474862, 2024).